CTSF (cathepsin F)
Diseases named in the same sentence as CTSF in open-access papers (continued):
Sharing a sentence is not in itself a finding about the gene and the disease.
colorectal cancer (1 paper, 2025). A primary or metastatic malignant neoplasm that affects the colon or rectum. "Our research also indicates that CTSF is a risk gene for colorectal cancer." (PMID 40381082, 2025). "We discovered that 428 DEGs had a causal association with colorectal cancer through eQTL, of which 38 genes met the FDR statistical standards, and four of these genes (CTSF, PCSK7, LYZ, LMAN2L) also had causal associations through pQTL." (PMID 40381082, 2025). "By integrating single-cell data, transcriptomic data, proteomic data and GWAS data for MR analysis, we identified CTSF, PCSK7, LYZ, LMAN2L as potential targets for colorectal cancer." (PMID 40381082, 2025). "This study identified CTSF, PCSK7, LYZ, and LMAN2L as critical regulatory genes in colorectal cancer, demonstrating their multifaceted clinical potential in diagnosis, therapeutic intervention, and prognostic evaluation." (PMID 40381082, 2025).
dermatitis (1 paper, 2023). An inflammatory process affecting the skin. "Cathepsin F (CTSF) has been implicated in dermatitis and various cancers and participates in cell immortalization through its association with Bcl family proteins." (PMID 36057013, 2023). "In contrast, in adipose stem cells, apoptosis is suppressed and cathepsin F expression is downregulated, thereby reducing radiation-induced dermatitis." (PMID 36057013, 2023).
diabetic maculopathy (1 paper, 2025). Diabetic maculopathy (DM) is a type of diabetic retinopathy and it is a major eye complication and visual impairment amongst people with diabetes. "Additionally, increased levels of Cathepsin F decrease the risk of diabetic maculopathy (OR = 0.9010, 95% CI = 0.8205–0.9895, P = 0.0292)." (PMID 40616157, 2025). "Cathepsin F showed a protective effect against diabetic maculopathy (OR = 0.9068, 95% CI = 0.8274–0.9938, P = 0.0364)." (PMID 40616157, 2025). "Equally intriguing is the protective role of Cathepsin F against diabetic maculopathy in our GSMR and IVW-MR analysis." (PMID 40616157, 2025). "Therefore, the IVW-MR further confirmed the GSMR results for Cathepsin H on DR, PDR and diabetic maculopathy, and cathepsin F on diabetic maculopathy." (PMID 40616157, 2025). "However, no statistically significant causal association was observed between Cathepsin H and DN, Cathepsin H and DR, or Cathepsin F and diabetic maculopathy, after adjusting for other types of cathepsins." (PMID 40616157, 2025).
Gaucher disease (1 paper, 2019). Gaucher disease (GD) is a lysosomal storage disorder encompassing three main forms (types 1, 2 and 3), a fetal form and a variant with cardiac involvement (Gaucher disease - ophthalmoplegia - cardiovascular calcification or Gaucher-like disease). "Several of the proteins that we found to be differentially expressed/abundant in Fabry CMs or in the extracellular space have known roles in other LSDs (including Gaucher disease, SCARB2/LIMP-2 and GBA; Krabbe disease, GALC; and ceroid lipofuscinosis, CTSF), but had never been implicated in FD." (PMID 31378672, 2019).
glioma (1 paper, 2023). A benign or malignant brain and spinal cord tumor that arises from glial cells (astrocytes, oligodendrocytes, ependymal cells). "Thus, we performed quantitative real-time PCR (qRT-PCR) analyses, which confirmed that CTSH, CTSO, CTSF, CTSK, CTSS, CTSV and CTSB were significantly downregulated in glioma cells treated with ar-turmerone." (PMID 37768200, 2023).
hepatocellular carcinoma (1 paper, 2022). A malignant tumor that arises from hepatocytes. "This indicated that different threshold expression levels of CTSF may facilitate the diagnosis of early-stage NSCLC and BM, and predict the risk of BM, similar to alpha fetal protein (AFP), a biomarker widely applied for the diagnosis of hepatocellular carcinoma (HCC)." (PMID 35217799, 2022).
lymph node metastasis (1 paper, 2021).
paragonimiasis (1 paper, 2023). A parasitic infection caused by trematodes of the Paragonimus genus. "The potential of cathepsin F, along with other antigenic candidates, merits further exploration for the development of diagnostic kits that offer enhanced sensitivity and specificity for paragonimiasis." (PMID 38251203, 2023). "Lately, the cathepsin F gene expression has been detected at different developmental stages of P. westermani worms, and the recombinant protein expressed was found to be highly immunoreactive with paragonimiasis patient sera." (PMID 38251203, 2023).
primary brain tumour (1 paper, 2022). "CTSF and Fibulin-1 (FBLN1) levels were specifically upregulated in sera and tissues of patients with NSCLC BM compared with NSCLC without BM and primary brain tumour." (PMID 35217799, 2022).
prostate carcinoma (1 paper, 2022). A carcinoma that arises from epithelial cells of the prostate gland. "We found that splice-disrupt variants on CTSF and PTPRC is specific to MCRPC and may contribute to prostate cancer progression." (PMID 35286517, 2022). "Splice-disrupt variants on CTSF and PTPRC is specific to MCRPC and may contribute to prostate cancer progression." (PMID 35286517, 2022).
renal carcinoma (1 paper, 2025). A carcinoma arising from the epithelium of the renal parenchyma or the renal pelvis. "CTSF’s causal role in renal cancer is similarly functionally supported." (PMID 41188181, 2025).
tumor (10 papers, 2005 to 2025). "Furthermore, downregulation of CTSF expression in GC tissues was associated with tumor invasion, differentiation and lymph node metastasis." (PMID 38891048, 2024). "Divergent LYZ and LMAN2L endothelial trends, coupled with cohort-specific CTSF dynamics in T cell subsets, underscore spatial or molecular heterogeneity in tumor microenvironments." (PMID 40381082, 2025). "After knocking down CTSF expression using CTSF-Lenti-shRNA, there was a notable increase in GC cell growth and a simultaneous reduction in apoptosis levels, further confirming CTSF’s tumor-suppressive function." (PMID 40381082, 2025). "While recent studies have shown increased expression of CTSF in various cancer cell lines, the exact role of this enzyme in tumor initiation, progression and prognosis remains elusive." (PMID 38891048, 2024). "We found that the expression level of CTSF was downregulated in tumor tissues and closely related to the poor survival of ccRCC patients." (PMID 38866930, 2024). "Gene–gene interaction analysis showed that CTSF activity is associated with genes involved in immune responses, and immunostaining showed higher expression of CTSF in macrophages and other infiltrating immune cells compared to tumor cells." (PMID 38891048, 2024). "CTSF (Cathepsin F), a lysosomal protease family member, participates in protein breakdown and autophagy, contributing to immune regulation, programmed cell death, and tumor microenvironment modulation." (PMID 40381082, 2025). "It remains unclear whether this differential tumour-metastatic activity of CTSF in different organs is attributed to tissue-specific substrates, or to alternative mechanisms of tissue-specific proteolytic regulation." (PMID 35217799, 2022). "It has been suggested in CTSF gene may function as a tumour suppressor with high potential therapeutic value." (PMID 35286517, 2022). "Although analysis of the resected tissues is invaluable in establishing the utility of expression of CTSF as a prognostic indicator, determining the circulating CTSF in serum is a convenient non-invasive method that can provide useful information about tumour malignancy." (PMID 35217799, 2022). "All 8 samples investigated by means of cDNA arrays showed increased CTSF expression, and in line with this, the tumor band intensities in agarose gels, as compared with the control band intensity, were increased from an average of 1.2 to 7 fold in all tumors for CTSF in the RT-PCR analyses." (PMID 15989693, 2005). "Cathepsin F transcripts were also found in several cancer cell lines, suggesting that this enzime could be involved in degradative processes during tumor progression." (PMID 15989693, 2005). "Understanding the role of CTSF and CTSW in tumor initiation and progression is essential for the development of novel prognostic biomarkers and immunotherapies." (PMID 38891048, 2024). "CTSF and AKR1B10 staining were notably dominant in the cytoplasm of tumour cells while FBLN1 staining was also observed in the interstitial cells in addition to the cytoplasm of tumour cells." (PMID 35217799, 2022). "We examined the expressions of CTSF, FBLN1 and AKR1B10 in BM tissues of 47 patients with NSCLC BM using IHC (cohort 3); 10 of these patients underwent orthotopic tumour excision in the early stages of the disease and the corresponding primary tumour tissues were also obtained." (PMID 35217799, 2022).
cancer (9 papers, 2005 to 2025). A tumor composed of atypical neoplastic, often pleomorphic cells that invade other tissues. "Several human cancer cell lines have increased expression of CTSF compared to its normal counterpart." (PMID 15989693, 2005). "Notably, downregulation of zebrafish orthologues for MMP23B, MMP28, and CTSF are consistent with downregulated expression of these genes in several human cancer types." (PMID 39511408, 2025). "Similarly, CTSF, known for its significant involvement in the progression of various cancers, neurodegenerative diseases, and skin aging, garners attention." (PMID 38304232, 2023). "Eight proteins (A4GALT, ASIP, CTSF, MARE1, PDXK, SEM4A, PLAUR, VARS1) were observed to have evidence of multi-trait colocalization between the index protein, intermediate phenotypes, and the index cancer endpoint, which may serve to elucidate aetiological pathways to cancer risk." (PMID 38684708, 2024). "Using the Pan-Cancer TCGA dataset gathering RNA-seq data from 11,060 patients, an anticorrelation between TET2 expression and mRNA levels of lysosome proteins was confirmed for CLN3, CTSD, CTSF, CTSZ, IFI30, and NAGLU, suggesting TET2 might down-regulate lysosomal genes in various types of cancer." (PMID 35351824, 2022).
infection (2 papers, 2021 to 2025). The state of being infected such as from the introduction of a foreign agent such as serum, vaccine, antigenic substance or organism. "For Mtb, we found out early that during establishment of the infection, the pathogen downregulates most cathepsins and that, with the exception of cathepsin F, most of these proteases were implicated in pathogen killing." (PMID 34867965, 2021).
neurological disease (2 papers, 2019 to 2024). "The CLN13 gene encodes cathepsin F (CTSF) and mutations in this gene were originally reported in mice, which develop neurological disease with accumulation of autofluorescent material in neurons of the cerebral cortex, hypothalamus, cerebellar Purkinje cells and other regions of the brain." (PMID 30651094, 2019). "Variants in the CTSF gene were first described in mice, where CTSF-deficient mice showed symptoms of neurological disease from 12 to 16 months of age with lack of motor coordination, progressive hind limb weakness, significant weight loss and premature death." (PMID 38891048, 2024).
digestive system tumors (1 paper, 2024). "This analysis encompassed a total of nine cathepsins include cathepsin B, cathepsin E, cathepsin F, cathepsin G, cathepsin H, cathepsin L2, cathepsin O, cathepsin S, and cathepsin Z, and six digestive system tumors (HCC, PCa, BTC, CRC, GC, and EC)." (PMID 38590662, 2024).
CTSF also shares sentences with these, for which no sentence is quoted: Alzheimer disease (3 papers); Adult onset (2); neurodegenerative disease (2); non-small cell lung carcinoma (2); -phosphoglycerate dehydrogenase deficiency (1); 3-methylglutaconyl-CoA hydratase deficiency (1); abetalipoproteinemia (1); Ataxia (1); Brain atrophy (1); cerebellar ataxia (1); chronic obstructive pulmonary disease (1); coproporphyria (1); depression (1); frontotemporal dementia (1); Intellectual disability (1); Kaya-Barakat-Masson syndrome (1); Krabbe disease (1); multiple sclerosis (1); progressive myoclonus epilepsy (1); pulmonary arterial hypertension (1); schizophrenia (1); skin cancer (1); sphingolipidoses (1); Tremor (1); Wolman disease (1).